NOTCH4 (notch receptor 4)
Diseases named in the same sentence as NOTCH4 in open-access papers (continued):
Sharing a sentence is not in itself a finding about the gene and the disease.
adenoma (2 papers, 2017 to 2020). A neoplasm arising from the epithelium. "KrasG12D upregulates expressions of Notch2, Notch3, Notch4, Jag1 and downstream target genes Hes1, Hey1 and Hey2, and deletion of Jag1 partially suppresses KrasG12D-induced adenoma development." (PMID 29142904, 2017). "Comparatively, in adenomas, ≥2-fold Notch3 expression was detected in 56% followed by Notch1 (44%), Notch4 (33%), and Notch2 (11%), while for ligand Jag1, mRNA was overexpressed in 33%, Jag2, Dll1, and Dll3 in 11%, whereas Dll4 was not expressed in adenomas." (PMID 32211044, 2020).
colon adenocarcinoma (2 papers, 2020 to 2023). "In samples of colon adenocarcinoma, the positive immunohistochemical reaction indicating the presence of Notch4 protein was observed in the cytoplasm and nucleus of cancer cells." (PMID 37108670, 2023). "It should be mentioned that in our cohort of patients, approximately 78% of colon adenocarcinoma specimens demonstrated high Notch4 protein expression, while low levels of immunoreactivity were found only in 22% of cases." (PMID 37108670, 2023). "In this place, it should be pointed out that our study is the first which demonstrate immunohistochemical expression of Notch4 in colon adenocarcinoma tissues in patients from European populations." (PMID 37108670, 2023). "Results of our study demonstrated that expression of Notch4 in colon adenocarcinoma tissue was clearly upregulated in comparison to that observed in the healthy tissue of the surgical margin." (PMID 37108670, 2023). "In colon adenocarcinoma cells, the black granules indicating the presence of Notch4 antigen were localised in the cytoplasm." (PMID 37108670, 2023). "Based on the results obtained in the Cox regression model, Notch4 has been identified as a protein connected with the reduced 5-year survival of colon adenocarcinoma patients." (PMID 37108670, 2023). "We can conclude that high expression of Notch4 is correlated with poor prognosis of colon adenocarcinoma patients (log-rank, p < 0.001)." (PMID 37108670, 2023). "Among the study cohort, 101 (78.29%) colon adenocarcinoma samples showed a high level of immunohistochemical expression of Notch4 protein, whereas only 28 (21.71%) demonstrated a low level of immunoreactivity." (PMID 37108670, 2023). "Multivariate analysis found that, in our cohort of patients, the degree of histological differentiation and Notch4 expression is regarded as independent predictors related to 5-year survival in patients with colon adenocarcinoma." (PMID 37108670, 2023). "The prognostic significance of Notch4 expression in colon adenocarcinoma patients was analysed in relation to a 5-year survival rate." (PMID 37108670, 2023). "Colon adenocarcinoma patients with a higher mRNA expression of Notch3, Notch4, and Hey1 presented significantly a shorter overall survival compared to those with low expression." (PMID 32211044, 2020). "The multivariate analysis revealed that the grade of histological differentiation and immunohistochemical expression of Notch4 in colon adenocarcinoma tissue could be considered independent prognostic factors." (PMID 37108670, 2023). "Therefore, the aim of our research was also to determine Notch4 intracellular localisation within the cells of colon adenocarcinoma tissue by the use of the immunogold labelling method and TEM." (PMID 37108670, 2023). "With this in mind, we decided to investigate the expression of Notch4 protein in European (Polish) patients with colon adenocarcinoma without any therapy prior to radical surgery." (PMID 37108670, 2023).
cryoglobulinemia (2 papers, 2022 to 2024). Cryoglobulinemia is a type of vasculitis that is caused by abnormal proteins (antibodies) in the blood called 'cryoglobulins.' At cold temperatures, these proteins become solid or gel-like, which can block blood vessels and cause a variety of health problems. "A study of 803 patients with positive HCV RNA described a significant association between chromosome 6 abnormalities, major histocompatibility complex (MHC) class II, Notch receptor 4 (NOTCH4) genes, and cryoglobulinemia-induced vasculitis." (PMID 36043014, 2022).
endothelial dysfunction (2 papers, 2020 to 2024). In vascular diseases, endothelial dysfunction is a systemic pathological state of the endothelium (the inner lining of blood vessels) and can be broadly defined as an imbalance between vasodilating and vasoconstricting substances produced by (or acting on) the endothelium. "Moreover, type I inflammation-mediated dysregulation of Notch4 signaling is involved in endothelial dysfunction." (PMID 33260695, 2020).
glioblastoma (2 papers, 2020 to 2025). The most malignant astrocytic tumor (WHO grade IV). "In vitro assays identified the expression of Notch1 and Notch4 receptors, with Notch1 being strongly expressed in low-grade gliomas and low in glioblastomas, whereas Notch4 is upregulated in glioblastoma and astrocytomas." (PMID 32796631, 2020).
Granuloma (2 papers, 2023). A compact, organized collection of mature mononuclear phagocytes, which may be but is not necessarily accompanied by accessory features such as necrosis. "The lung tissue sections surgically removed from TB patients were analyzed by immunohistochemistry with anti-Notch4 antibodies, and normal tissue next to the granulomas of TB patients as a control." (PMID 36817473, 2023). "We further detected Notch4 expression in granulomas of tuberculosis." (PMID 36817473, 2023).
heart failure (2 papers, 2013 to 2024). Inability of the heart to pump blood at an adequate rate to meet tissue metabolic requirements. "Although literature has shown that the Notch signaling system exists in myocardial cells and is activated during heart failure, and Notch3 and Notch4 may be the main receptors involved, more studies have reported a close relationship between Notch1 and cardiovascular disease." (PMID 38841263, 2024).
Hepatic fibrosis (2 papers, 2021). The presence of excessive fibrous connective tissue in the liver. "In the CCl4-induced liver fibrosis rat experiment, qPCR showed that the mRNA expressions of Jagged1, Jagged2, Notch2, Notch3, Notch4 and recombination signal binding protein-κB (RBP-κB) were significantly more upregulated in the CCl4 group than those in the control group." (PMID 34630075, 2021). "Although the expression of Notch1 and Notch4 decreased during the progression of hepatic fibrosis, the expression pattern of Hes1, a target gene downstream of Notch signaling, was similar to Notch3 and Jagged1, fluctuated with the progression and regression of hepatic fibrosis." (PMID 34239344, 2021). "While in CCl4-induced liver fibrosis mice experiment, JY5 not only decreased the mRNA expressions of Jagged1, Notch2, Notch3, Notch4 and RBP-κB, but also downregulated the expression of Dll1." (PMID 34630075, 2021). "Consistent with the CCl4-induced rat liver fibrosis model, JY5 decreased the expressions of Jagged1, Notch2, Notch3, Notch4 and RBP-κB in the BDL-induced liver fibrosis model." (PMID 34630075, 2021). "In this study, the expressions of Jagged1, Jagged2, Notch2, Notch3, Notch4, and RBP-κB were significantly increased in CCl4-and BDL-induced liver fibrosis in rats and mice." (PMID 34630075, 2021).
HIV-associated nephropathy (2 papers, 2019 to 2020). Renal disease in human immunodeficiency virus (HIV)-infected patients. "In addition, the Notch4 expression was found to be upregulated in various renal cells in patients with HIV-associated nephropathy (HIVAN) and in rodent models of HIVAN." (PMID 33149805, 2020).
infiltrating ductal carcinoma (2 papers, 2013 to 2017). "Next, we examined human biopsy samples (n=6) from infiltrating ductal carcinoma, which were immunostained with an antibody against Notch4." (PMID 23601498, 2013).
influenza (2 papers, 2023). An acute viral infection of the respiratory tract, occurring in isolated cases, in epidemics, or in pandemics; it is caused by serologically different strains of viruses (influenzaviruses) designated A, B, and C, has a 3-day incubation period, and usually lasts for 3 to 10 days. "For example, Notch4 is upregulated in lung tissue Tregs during SARS-CoV2 and influenza infections, leading to enhanced tissue inflammation and disease severity." (PMID 36282598, 2023). "Thus, Notch4 appears critical for licensing lung inflammation following SARS-CoV2, influenza, and related viral infections." (PMID 36282598, 2023). "Notch4 and Fgfr1 represent only two of several putative candidates that may regulate lung endothelial apoptosis and proliferation after H1N1 infection, and the role of these and other pathways in the EC response to influenza merit further evaluation in future studies." (PMID 37233732, 2023).
Insulin resistance (2 papers, 2015 to 2019). Increased resistance towards insulin, that is, diminished effectiveness of insulin in reducing blood glucose levels. "Notch homolog 1 (NOTCH1) and NOTCH4 are components of the Notch signaling pathway, and activation of the Notch signaling pathway is important for the improvement of insulin resistance." (PMID 30678306, 2019).
intrahepatic cholangiocarcinoma (2 papers, 2021 to 2023). A carcinoma that arises from the intrahepatic bile duct epithelium in any site of the intrahepatic biliary tree. "In contrast, in patients with intrahepatic cholangiocarcinoma, the high Notch4 expression correlates with high serum CA125 levels." (PMID 37108670, 2023).
lymphoma (2 papers, 2020 to 2021). A malignant (clonal) proliferation of B- lymphocytes or T- lymphocytes which involves the lymph nodes, bone marrow and/or extranodal sites. "On this basis, another study confirmed the significant relationship between this allelic variant and an increased lymphoma risk in a group of patients with HCV-related lymphomas, suggesting Notch 4 polymorphism as a possible non-invasive marker of hematological malignancy." (PMID 33374160, 2020). "In our results, some of the differentially methylated genes in EHMT2 + MCL cases have also been reported with recurrent genetic alterations in lymphoma, such as ALK, DUSP22, NCOR2, RORA, DLC1, JAG1/2, JAK1, NOTCH4, and CD1938–45." (PMID 34633777, 2021).
lymphoproliferative disorders (2 papers, 2017 to 2024). "We analyzed NOTCH4 rs2071286 and HLA-II rs9461776 in 3 HCV-related LPD groups (asymptomatic MC, MCS, NHL) with HCV infection without lymphoproliferative disorders." (PMID 29069725, 2017).
metastatic melanoma (2 papers, 2020 to 2023). A melanoma that has spread from its primary site to another anatomic site. "Notch4 and Nodal have been identified as two critical signaling proteins in metastatic melanoma which contribute to VM formation." (PMID 37351538, 2023). "Patient follow-up indicated that cases with metastatic melanoma had previously exhibited high Cripto, Nodal, and Notch4 (inducer of Nodal) expression." (PMID 32517087, 2020).
neonatal lupus (2 papers, 2012 to 2020). "The recent SLE susceptible loci identified in the cardiac manifestation of neonatal lupus, NOTCH4, was found in our results." (PMID 32771030, 2020).
oral squamous cell carcinoma (2 papers, 2019 to 2023). "Thus the present study aims in determining the differential expression pattern of Notch4 in oral verrucous carcinoma and oral squamous cell carcinoma." (PMID 29162408, 2019). "These preliminary findings strongly support the fact that Notch4 is downregulated in oral verrucous carcinoma and could be considered as a suitable prognostic marker in distinguishing oral verrucous carcinoma from oral squamous cell carcinoma." (PMID 29162408, 2019). "Our results reveal that the expression of Notch4 was considerably high in oral squamous cell carcinoma lesions compared to normal tissue, whereas in oral verrucous carcinoma, irrespective of the clinicopathological features, complete regulação descendente of Notch4 was observed." (PMID 29162408, 2019).
psoriatic arthritis (2 papers, 2020 to 2024). Joint inflammation associated with psoriasis. "NOTCH4 was also reported to be associated with psoriasis arthritis, and notch signaling pathways were found to mediate synovial angiogenesis in psoriatic arthritis." (PMID 33134369, 2020).
renal carcinoma (2 papers, 2015 to 2021). A carcinoma arising from the epithelium of the renal parenchyma or the renal pelvis. "In renal carcinoma tissue, the level of Notch-4 is significantly decreased or almost absent, though it inversely correlates with tumor progression." (PMID 34337053, 2021).
renal cell carcinoma (2 papers, 2019 to 2021). "Whereas in some cancer types such as renal cell carcinoma, downregulation of Notch4 has been reported." (PMID 29162408, 2019).
scleroderma (2 papers, 2016 to 2024). Scleroderma is a rare autoimmune connective tissue disorder characterized by abnormal hardening of the skin and, sometimes, other organs. "Here we have described a very rare amino acid substitution in a putative regulatory region of NOTCH4 segregating in a family with SSc/scleroderma." (PMID 27829420, 2016). "We note that the mother of the proband appears disease-free despite carrying the exact same NOTCH4 p.Met1415Ile variant and without the expression of scleroderma." (PMID 27829420, 2016).
small cell lung carcinoma (2 papers, 2024 to 2025). Small cell lung cancer (SCLC) is a highly aggressive malignant neoplasm, accounting for 10-15% of lung cancer cases, characterized byrapid growth, and early metastasis. "In small-cell lung cancer (SCLC), the prevalence of loss-of-function mutations of Notch proteins is reported to be about 25–28%, with Notch1 being the most frequently mutated, followed by Notch2, Notch4, and Notch3." (PMID 39766289, 2024).
tuberculosis (2 papers, 2021 to 2023). A chronic, recurrent infection caused by the bacterium Mycobacterium tuberculosis. "Interestingly, Jingwei Zhang and his colleagues also found Notch4 missense mutation rs422951 was associated with susceptibility to tuberculosis in Chinese population and the G variants of rs422951 conferred protective factors in TB susceptibility." (PMID 36817473, 2023). "However, other studies show that a Notch4 missense mutation is associated with an increased susceptibility to tuberculosis in the Chinese population." (PMID 34925319, 2021). "Distribution and frequencies of Notch4 genotype with different genetic models in tuberculosis patients and controls." (PMID 36817473, 2023). "In conclusion, Notch4 is involved in the occurrence and development of tuberculosis." (PMID 36817473, 2023). "To investigate the expression levels of Notch4 in pulmonary tuberculosis, we first explored Notch4 expression in PBMCs from TB patients." (PMID 36817473, 2023). "However, Notch4 expression level and clinical significance in tuberculosis remains uncertain." (PMID 36817473, 2023).
acral lentiginous melanoma (1 paper, 2022). A form of melanoma occurring most often on the plantar, palmar, subungual, and periungual skin. "The predictive performance of NOTCH4 in acral lentiginous melanoma and mucosal melanoma needs to be further explored." (PMID 35967450, 2022).
anxiety disorder (1 paper, 2025). A category of psychiatric disorders which are characterized by anxious feelings or fear often accompanied by physical symptoms associated with anxiety. "However, the fact that glucocorticoid signaling has been shown to activate Notch4 transcription suggests a potential relevance in the pathogenesis of stress-related disorders such as anxiety disorders as well." (PMID 40281224, 2025).
autoimmune disorders (1 paper, 2017). "Among the notch family, NOTCH4 and its signaling is the least studied member; as already mentioned, several reports showed an association between SNPs either within or near NOTCH4 and different autoimmunities, but, so far, no indication about its functional role has been proposed." (PMID 29069725, 2017).
B cell lymphoma (1 paper, 2011). "This minireview focuses on recent advances related to the mechanisms and roles of activated Notch1, Notch2, Notch3 and Notch4 signaling in human lymphocytic leukemia, myeloid leukemia and B cell lymphoma, as well as their significance, and recent advances in Notch-targeted therapies." (PMID 22128846, 2011).
breast ductal carcinoma (1 paper, 2021). "Abnormal expressions of Notch-1, Notch-4 or Jagged-1 are common in breast ductal carcinoma and lobular carcinoma." (PMID 34872446, 2021).
bronchopulmonary dysplasia (1 paper, 2025). Bronchopulmonary dysplasia is a chronic respiratory disease that results from complications related to lung injury during the treatment of infant acute respiratory distress syndrome in low-birth-weight premature infants or from abnormal lung development in older infants.
central obesity (1 paper, 2022). "In large genome-wide human association studies, variation in Notch4 gene was associated with central obesity measures and triacylglycerol levels." (PMID 36014934, 2022).
CHARGE syndrome (1 paper, 2005). CHARGE syndrome is a multiple congenital anomaly syndrome characterized by the variable combination of multiple anomalies, mainly Coloboma; Choanal atresia/stenosis; Cranial nerve dysfunction; Characteristic ear anomalies (known as the major 4 C's). "Since TOF is a heart defect commonly seen in CHARGE Syndrome, NOTCH4 was further studied with FISH as well as flanking SNP markers for microdeletion." (PMID 15710038, 2005).
colorectal adenocarcinoma (1 paper, 2023). The most common type of colorectal carcinoma. "The immunogold labelling method was used to reveal the localisation of Notch4 protein at the cellular level within colorectal adenocarcinoma tissues and in non-neoplastic cells from surgical margins." (PMID 37108670, 2023).
colorectal tumors (1 paper, 2020). "Among the receptors, aberrant Notch3 and Notch4 overexpressions were observed in high percentage of colorectal tumors seen in 44/66 (73%) and 37/66 (56%) cases, respectively." (PMID 32211044, 2020).
ductal carcinoma in situ (1 paper, 2021). "Likewise, a Notch4-neutralizing antibody reduced the tumorsphere-forming efficiency of cancer cells isolated from primary ductal carcinoma in situ, thus suggesting that Notch4 disruption would be therapeutically useful for the treatment of this cancer." (PMID 34680255, 2021).
eczema (1 paper, 2021). "Selecting variants based on the deleteriousness score (CADD) in combination with the variance-component test (SKAT) performed best for the different scenarios and identified FLG, DUSP1, and NOTCH4 to be significantly associated with eczema in RV set." (PMID 34785669, 2021). "All significantly associated genes within the EDC and within the MHC disappeared suggesting that the best-associated genes FLG and NOTCH4 represented the main eczema-susceptibility genes in these regions." (PMID 34785669, 2021). "As identified in RV set, MAGMA confirmed FLG, DUSP1, and NOTCH4 to be significantly associated with eczema in the complete data set." (PMID 34785669, 2021). "The localization of the missense variants and their potential functional impact on the newly-identified eczema-associated genes DUSP1 and NOTCH4 suggest promising targets for future therapies." (PMID 34785669, 2021). "In our meta-GWAS on rare variants in eczema, we uncover disease-associated exonic variants in the genes encoding dual specificity phosphatase 1 (DUSP1), neurogenic locus notch homolog protein 4 (NOTCH4), and solute carrier family 9 member A4 (SLC9A4)." (PMID 34785669, 2021). "We identify rare exonic variants in DUSP1, NOTCH4, and SLC9A4 to be associated with eczema." (PMID 34785669, 2021). "Functional studies will be required to confirm a role of NOTCH4 in eczema." (PMID 34785669, 2021).